SLC4A10 (solute carrier family 4 member 10)
Description:
Sodium/bicarbonate cotransporter which plays an important role in regulating intracellular pH. Has been shown to act as a sodium/bicarbonate cotransporter in exchange for intracellular chloride (By similarity). Has also been shown to act as a sodium/biocarbonate cotransporter which does not couple net influx of bicarbonate to net efflux of chloride, with the observed chloride efflux being due to chloride self-exchange. Controls neuronal pH and may contribute to the secretion of cerebrospinal fluid (By similarity). Acting on presynaptic intracellular pH, it promotes GABA release, reduces the excitability of CA1 pyramidal neurons, and modulates short-term synaptic plasticity (By similarity). Required in retinal cells to maintain normal pH which is necessary for normal vision (By similarity). In the kidney, likely to mediate bicarbonate reclamation in the apical membrane of the proximal tubules (By similarity).
Synonyms: NBCN2; NCBE
Tractability: Antibody: its Gene Ontology location is reachable by antibodies, with high confidence; UniProt places it where antibodies can reach, with medium confidence; UniProt predicts a signal peptide or a membrane-spanning region. PROTAC: ubiquitination databases record sites on it; its protein half-life has been measured.
Gene: Protein-coding gene on chromosome 2 (161,424,332 to 161,985,282, forward strand). Ensembl gene ENSG00000144290.
Subcellular location: Basolateral cell membrane; Apical cell membrane; Cell projection, dendrite; Cell projection, axon; Perikaryon; Presynapse; Postsynapse
Pathways (Reactome):
Transport of small molecules: Bicarbonate transporters
Gene Ontology:
Molecular function: sodium:bicarbonate symporter activity; solute:inorganic anion antiporter activity; bicarbonate transmembrane transporter activity; monoatomic anion transmembrane transporter activity; secondary active transmembrane transporter activity; sodium,bicarbonate:chloride antiporter activity
Biological process: bicarbonate transport; chloride transport; regulation of intracellular pH; regulation of short-term neuronal synaptic plasticity; visual perception; monoatomic anion transmembrane transport; monoatomic anion transport; monoatomic ion transport; sodium ion transmembrane transport; transmembrane transport
Cellular component: apical plasma membrane; axon terminus; basolateral plasma membrane; dendrite; GABA-ergic synapse; membrane; neuronal cell body; perikaryon; plasma membrane; postsynapse; presynapse; somatodendritic compartment; synapse; apical dendrite; axon; basal dendrite; CA3 pyramidal cell dendrite
Genetic constraint (gnomAD): Loss-of-function variants: 28 observed, 95.3 expected, observed/expected ratio (o/e) 0.29, 90% interval 0.22 to 0.4. The upper end of that interval is the gene's LOEUF score, 0.4, which puts it in group 1 of 6, group 1 being the genes least tolerant of losing a copy. Missense variants: 751 observed, 1,120.1 expected, observed/expected ratio (o/e) 0.67, 90% interval 0.63 to 0.71. Synonymous variants: 400 observed, 390.21 expected, observed/expected ratio (o/e) 1.03, 90% interval 0.94 to 1.11.
Gene-disease validity (ClinGen):
ClinGen rates the evidence that SLC4A10 causes each of these diseases.
complex neurodevelopmental disorder (autosomal recessive): Strong. A disorder that involves more than one phenotype associated with the central nervous system, including but not limited to intellectual disability, autism, and seizures (epilepsy).
Homologues: Orthologues: rabbit SLC4A10 (99% identical), guinea pig SLC4A10 (99% identical), chimpanzee SLC4A10 (98% identical), dog SLC4A10 (98% identical), macaque SLC4A10 (97% identical), mouse Slc4a10 (95% identical), rat Slc4a10 (95% identical), pig SLC4A10 (94% identical), tropical clawed frog slc4a10 (85% identical), zebrafish slc4a10a (79% identical), zebrafish slc4a10b (66% identical), Drosophila melanogaster Ndae1 (50% identical), and 3 more. Paralogues in human: SLC4A8 (75% identical), SLC4A7 (73% identical), SLC4A4 (52% identical), SLC4A5 (47% identical), SLC4A9 (39% identical), SLC4A2 (36% identical), SLC4A3 (35% identical), SLC4A1 (30% identical), SLC4A11 (20% identical).
Diseases named in the same sentence as SLC4A10 in open-access papers:
SLC4A10 is named in the same sentence as 32 diseases in open-access papers, as found by Europe PMC text mining. Sharing a sentence is not in itself a finding about the gene and the disease. The quoted sentences say what the papers report.
epilepsy (7 papers, 2012 to 2023). A brain disorder characterized by episodes of abnormally increased neuronal discharge resulting in transient episodes of sensory or motor neurological dysfunction, or psychic dysfunction. "SLC4A10 is widely reported as a candidate risk-related gene for some neuro-related disorders linked with neuronal excitability, such as epilepsy, autism and major depressive disorder (MDD)." (PMID 27716781, 2016). "Other NOVA-NMD related targets in which gene mutations have been implicated in human epilepsy include the anion transporters SLC4a10 and SLC4a3." (PMID 23359859, 2013). "Disruption of sodium bicarbonate transporter SLC4A10 it has also been associated with mental retardation and epilepsy." (PMID 22214275, 2012). "Furthermore, in humans, the SLC4A10 (NBCn2) gene-locus is linked with epilepsy and autism." (PMID 24592239, 2014). "In light of the evidence that bicarbonate transporters of the SLC4A family including SLC4A10 are involved in seizure disorders, a better understanding of their role for synaptic transmission is desirable to get a more comprehensive view of neuronal excitability and the pathophysiology of epilepsy." (PMID 26136660, 2015).
Cognitive impairment (2 papers, 2023 to 2025). Abnormal cognition is characterized by deficits in thinking, reasoning, or remembering. "The identification of biallelic SLC4A10 variants in affected individuals with cognitive impairment and behaviours associated with autistic spectrum disorder prompted us to reanalyse the behaviour of Slc4a10−/− mice." (PMID 37459438, 2023). "Loss-of-function NCBE variants have been associated with neurodevelopmental disease with impaired GABAergic transmission, and disruption of SLC4A10 has been reported in frontal lobe epilepsy with cognitive impairments." (PMID 41010403, 2025).
complex partial epilepsy (2 papers, 2019 to 2023). A disorder characterized by recurrent partial seizures marked by impairment of cognition. "Nonetheless, we note that chromosomal translocation involving the SLC4A10 gene in humans causes complex partial epilepsy and cognitive dysfunction." (PMID 31690738, 2019).
COVID-19 (2 papers, 2020 to 2022). A disease caused by infection with severe acute respiratory syndrome coronavirus 2. "For the MR analysis on transcripts, expression levels of two genes, LZTFL1 and SLC4A10, showed robust MR evidence on COVID-19 severity using data from GenOMICC." (PMID 35772218, 2022).
deafness (2 papers, 2023). An inherited or acquired condition characterized by the complete loss of the ability to hear from one or both ears. "Interestingly, in the case of Slc4a10, the early onset progressive deafness phenotype is reported in a knockout mutant maintained on a congenic C57BL/6J background." (PMID 37854703, 2023).
hearing loss (2 papers, 2016 to 2019). "In human, genetic abnormality in locus 2q24 spanning SLC4A10 is associated with complex epilepsy, mental retardation, autism spectra, cognitive disabilities, and hearing impairment." (PMID 31736772, 2019). "In mouse, genetic disruption of Slc4a10 reduces neuronal excitability, resulting in increased seizure threshold, impairs the visual acuity and contrast sensitivity, and causes hearing loss." (PMID 31736772, 2019).
Hypertension (2 papers, 2025). The presence of chronic increased pressure in the systemic arterial system. "GRAPPLE suggests pathways from DPP4 gene expression at the mRNA level to MI and stroke are notably influenced by factors such as BMI, SLC4A10, total cholesterol (TC), hypertension (HTN), and total triglyceride (TG)." (PMID 40904650, 2025).
Intellectual disability (2 papers, 2023 to 2024). "Case studies have shown that autosomal recessive loss of function of SLC4A10 leads to intellectual disability, microcephaly and lateral ventricle abnormalities." (PMID 38438384, 2024). "Patients with SLC4A10 loss-of-function not only suffer from intellectual disability and behavioural abnormalities, but also show microcephaly and characteristic slit-like brain ventricles." (PMID 37459438, 2023). "Here, we provide clinical, genetic, functional and mouse-model evidence to determine that autosomal recessive SLC4A10 loss-of-function results in intellectual disability with striking radiological abnormalities of the lateral ventricles, closely mirroring findings in Slc4a10 knockout (KO) mice." (PMID 37459438, 2023).
neuroblastoma (2 papers, 2015 to 2023). Neuroblastoma (NB) is the most common solid, extracranial childhood tumor. "Here, we examined, by using luciferase reporter assay, the cell specificity of transcriptional activities of the three promoters of rat Slc4a10 in human embryonic kidney cell HEK293, rat ganglion cell RGC-5, and neuro-2A cells which is a mouse neuroblastoma cell line." (PMID 26192895, 2015).
open-angle glaucoma (2 papers, 2010 to 2023). Chronic outflow obstruction of the eye's drainage canals that can lead to increased internal eye pressure and optic nerve damage. "Additionally, SLC4A10 is hypothesized to function in the pathology of primary open-angle glaucoma (POAG)." (PMID 37894847, 2023).
age-related hearing loss (1 paper, 2016). "As such, our findings suggest that trombone is likely a model of strial presbycusis, and that Slc4a10 is a candidate gene for human age-related hearing loss." (PMID 27534441, 2016).
Alzheimer disease (1 paper, 2023). A progressive, neurodegenerative disease characterized by loss of function and death of nerve cells in several areas of the brain leading to loss of cognitive function such as memory and language. "Significantly decreased expression of SLC4A10 helps explain reduced cerebrospinal fluid (CSF) formation and turnover in Alzheimer’s disease (AD), resulting in impaired clearance of toxic metabolites and neuroinflammation." (PMID 37789379, 2023).
atherosclerosis (1 paper, 2025). A disease characterized by the build-up of fatty material and calcium deposition in the arterial wall resulting in partial or complete occlusion of the arterial lumen. "AAV-6-induced overexpression of SLC4A10 in CD8+ T cells of mice resulted in a decreased severity of atherosclerosis, a reduced content of collagen fibers, and a decreased number of apoptotic VSMCs." (PMID 40510365, 2025). "We used AAV-6 to achieve overexpression of SLC4A10 in CD8+ T cells of mice and preliminarily examined the function of SLC4A10 in the advancement of atherosclerosis and plaque stability." (PMID 40510365, 2025). "We conducted a preliminary exploration of the role of SLC4A10+ CD8+ T cells in atherosclerosis and plaque stability." (PMID 40510365, 2025). "Our research on this newly discovered CD8+ T cell subset revealed that after overexpressing SLC4A10 in mice, the degree of atherosclerosis was mitigated, the content of collagen fibers was reduced, and the number of apoptotic VSMCs was decreased." (PMID 40510365, 2025). "It has been shown that overexpression of SLC4A10 leads to a reduction in the secretion of GZMB and IFN-γ, thereby attenuating the progression of atherosclerosis and facilitating the stable development of plaques." (PMID 40510365, 2025). "Therefore, SLC4A10+ CD8+ T cells serve as a cell subset with chronically stimulated and elevated responses to inflammation in atherosclerosis, exerting a protective effect on the development of atherosclerosis." (PMID 40510365, 2025). "In summary, this study supports the fact that SLC4A10 weakens the toxic functions of CD8+ T cells in secreting IFN-γ and GZMB via the MAPK pathway, exerting a significant role in decelerating the development of atherosclerosis and facilitating plaque stability." (PMID 40510365, 2025).
Stroke (1 paper, 2025). Sudden impairment of blood flow to a part of the brain due to occlusion or rupture of an artery to the brain. "Multivariate MR within the GRAPPLE framework revealed the impact of specific candidates like SLC4A10, BMI, TC, HTN, and TG on the MI and stroke pathways from DPP4 gene expression at the mRNA level." (PMID 40904650, 2025).
tumor (5 papers, 2020 to 2025). "While CD8A expression was higher in fetal‐type tumours, GZMK and SLC4A10 were more highly expressed in embryonal‐type tumours." (PMID 40099956, 2025).
neurological disorders (4 papers, 2021 to 2025). "Examples include SLC4A3 (AE3), which can act as a Cl− accumulator, and SLC4A10 (NCBE), which mediates sodium-dependent Cl− efflux while allowing bicarbonate influx and has been linked to neurological disorders." (PMID 41010403, 2025). "The DPP4 locus is flanked by the GCG gene (encoding proglucagon, the source of glucagon, GLP-1, and GLP-2) and the SLC4A10 gene, both of which have some shared characteristics, such as involvement in neurological disorders." (PMID 40904650, 2025).
neurodevelopmental disorder (2 papers, 2023). A behavioral and cognitive disorder with onset during the developmental period that involves impaired or aberrant development of intellectual, motor, or social functions. "Using next generation sequencing on samples from five unrelated families encompassing nine affected individuals, we show that biallelic SLC4A10 loss-of-function variants cause a clinically recognizable neurodevelopmental disorder in humans." (PMID 37459438, 2023). "In summary, we present extensive genetic, clinical, functional and murine datasets that confirm that biallelic SLC4A10 pathogenic loss-of-function gene variants cause a syndromic neurodevelopmental disorder." (PMID 37459438, 2023). "Together our studies define a novel neurodevelopmental disorder associated with biallelic pathogenic variants in SLC4A10 and highlight the importance of further analyses of the consequences of SLC4A10 loss-of-function for brain development, synaptic transmission and network properties." (PMID 37459438, 2023). "As SLC4A10 localizes to inhibitory presynapses and its disruption compromises γ-aminobutyric acid (GABA) release, we propose that alterations of the GABAergic system contribute to the pathomechanistic basis of this neurodevelopmental disorder." (PMID 37459438, 2023).
SLC4A10 also shares sentences with these, for which no sentence is quoted: autism (4 papers); glaucoma (2); microcephaly (2); Alkalosis (1); Anxiety (1); autistic spectrum disorder (1); cancer (1); colorectal cancer (1); developmental delay (1); frontal lobe epilepsy (1); infection (1); insulinoma (1); liver cancer (1); major depressive disorder (1); progressive cognitive decline (1).